FTO (FTO alpha-ketoglutarate dependent dioxygenase)
Diseases named in the same sentence as FTO in open-access papers (continued):
Sharing a sentence is not in itself a finding about the gene and the disease.
tumor (continued). "In addition, the overexpression of FTO suppressed tumor growth in vivo." (PMID 31143705, 2019). "However, anti-PD-1 antibody significantly inhibited tumor growth for FTO knockdown tumors." (PMID 31239444, 2019). "We observed that METTL3, WTAP and FTO transcript and protein expression were significantly increased in cells derived from invasive regions of GBM tumours, and elevated WTAP and FTO expression significantly correlated with poor GBM patient survival." (PMID 41752103, 2026). "Silencing FTO inhibited HCC cell proliferation, glycolysis, and tumor growth, and decreased the levels of circGDI2, IGF2BP2, and PKM2." (PMID 41439029, 2026). "A significant positive correlation was observed between the transcriptional levels of FTO and SRSF6 across multiple cancer types (including tumor and normal tissues) from the TCGA database." (PMID 40712780, 2025). "Researchers have shown that application of the SPI1 inhibitor DB2313 increases FTO expression and decreases the GBM tumour burden." (PMID 40469294, 2025). "FTO and IGFBP3 mRNA levels were both higher in tumour tissues than normal tissues, although the increase in IGFBP3 was not statistically significant." (PMID 40621649, 2025). "AURKB, a critical node downstream of the FTO/SP1/AURKB pathway, can modulate the tumor microenvironment of GC and drive its malignant progression." (PMID 41312360, 2025). "The writer enzyme METTL3 facilitates tumor growth by stabilizing oncogene mRNA, whereas erasers such as FTO and ALKBH5 suppress tumor progression by removing m6A marks." (PMID 40034695, 2025). "In lung adenocarcinoma (LUAD), FTO stabilizes PHF1 mRNA through demethylation, forming a tumor-suppressive axis." (PMID 40823093, 2025). "Silencing of FTO reduces glycolytic activity in tumor cells, leading to the restoration of CD8 + T cell function and inhibition of tumor growth." (PMID 39987091, 2025). "FTO, C-Jun and PFKM were individually detected using WB analysis in transgenic mouse primary tumor cells." (PMID 41184232, 2025). "Stable FTO promotes BLCA cell proliferation and migration in vitro and tumor development in vivo by decreasing the m6A methylation of pyrrolidine 5‐carboxylate reductase 1 (PYCR1) and lengthening the mRNA half‐life of PYCR1." (PMID 40919129, 2025). "Targeting these regulatory proteins (such as METTL3 inhibitors STM2457 and FTO inhibitors FB23-2) can reverse resistance and enhance the efficacy of immune checkpoint blockade, providing a new approach to overcoming tumor immune resistance." (PMID 41584846, 2025). "The downregulation of FTO promotes the expression of APOE and enhances glycolysis in PTC, thus promoting tumor growth." (PMID 40332101, 2025). "One study found that FTO works by inhibiting growth and glycolysis, likely by reducing the expression of APOE which acts to promote tumor growth via the IL-6/JAK2/STAT3 pathway." (PMID 40243425, 2025). "IHC and IF staining also revealed that FTO deletion decreased C-Jun and PFKM expression in tumor tissues and MDO." (PMID 41184232, 2025). "YTHDF3 translates m6A-rich transcripts and promotes brain metastasis of tumors; FTO regulates the stability and expression of PPARγ and C/EBP-α/β mRNA, and promotes tumor growth and lung metastasis." (PMID 41446042, 2025). "The expression of FTO and ALKBH5 has shown discrepancies in studies on RCC patients, with some indicating oncogenic roles and others suggesting tumor-suppressive roles." (PMID 40361322, 2025). "At the molecular level, FTO-mediated m6A demethylation stabilizes oncogenic drivers such as MALAT1 and CDK6, resulting in the formation of regulatory circuits that increase tumor cell proliferation, invasion, and chemoresistance." (PMID 40986143, 2025). "For instance, suppression of the demethylase FTO gene can attenuate the glycolytic activity of tumor cells, thereby reinstating the functionality of CD8+ T cells and impeding tumor growth." (PMID 40028341, 2025).
tumor (continued). "Saikosaponin D, GNPIPP12MA and ZLD115a, three novel FTO inhibitors, exhibit exceptional efficacy in inhibiting FTO’s activity on MYC mRNA, downregulating aerobic glycolysis and suppressing tumor progression." (PMID 41373022, 2025). "FTO depletion enhances KCNAB2 expression, thereby suppressing tumor cell migratory capacity, invasive potential, and M2 macrophage polarization." (PMID 40986143, 2025). "In IDH-mutant gliomas, slower tumor growth and better prognosis as compared to their IDH-wildtype counterparts are attributed to reduced FTO levels, another m6A demethylase." (PMID 40002173, 2025). "The study found that m6A and its writer protein METTL3, eraser protein FTO, and reader protein YTHDF2 play an essential role in CAFs promoting tumor cell metastasis and angiogenesis." (PMID 40356596, 2025). "Collectively, modulation of FTO, ALKBH5, or their downstream targets restores drug sensitivity and limits tumor relapse in preclinical models." (PMID 41228380, 2025). "In acute myeloid leukemia, inhibition of the demethylase FTO decreases the expression of immune checkpoint molecules such as PD-L1 and leukocyte immunoglobulin-like receptor (LILR)B4, enhancing tumor cell sensitivity to T cell-mediated cytotoxicity." (PMID 40176140, 2025). "While regulators like METTL3 and FTO largely drive oncogenesis, others, most notably METTL14, exert potent tumor-suppressive effects, underscoring the critical importance of context-specific understanding." (PMID 41312360, 2025). "Suppression of FTO significantly stabilizes apolipoprotein E (APOE) mRNA and coordinates with IGF2BP2, leading to the promotion of GLUT1 expression and tumor glycolysis by modulating the IL-6/JAK2/STAT3 signaling pathway." (PMID 41373022, 2025). "the results of the scratch assay and transwell assay showed that after antagonizing the downregulation of VEGFA by FTO in HCCLM3 cells, tumor invasiveness and migratory capacity were significantly upregulated." (PMID 40316995, 2025). "In our study, we identified that D-2HG accumulation inhibited the activity of FTO, leading to increased m6A modification of ANGPTL4, a protein known to promote tumor progression and metastasis." (PMID 39910592, 2025). "To further validate the effect of FTO on PDAC cell metastasis in vivo, we generated a hepatic metastatic xenograft model via intrasplenic injection of KPC or FKPC primary tumor cells." (PMID 41184232, 2025). "To verify the regulatory mechanism of the FTO/C-Jun/PFKM axis, we further executed C-Jun blocking experiments in KPC/FKPC primary tumor cells." (PMID 41184232, 2025). "Although FTO and ALKBH5 have oncogenic roles in the majority of cancers studied, they can also be tumor suppressors." (PMID 41373022, 2025). "The results showed that the expression of FTO and ALKBH5 was higher in NPC patients with tumor node metastasis (TNM) stages III and IV than in NPC patients with TNM stages I and II." (PMID 38263362, 2024). "The fat mass and obesity-associated gene (FTO) is a nuclear protein of the AlkB-related non-heme iron and 2-oxoglutarate-dependent oxygenase superfamily, playing a role in regulating energy metabolism, fat formation, cell differentiation, neurodevelopment, and tumor progression." (PMID 39295930, 2024). "This evidence suggests that FTO and ALKBH5 are carcinogenic and tumor suppressor factors, respectively, in hypoxia." (PMID 39033180, 2024). "Inhibition of FTO facilitated autophagic death of NSCLC cells and inhibited tumor growth via the GAS5/UPF1/BRD4 pathway." (PMID 38576024, 2024). "IGF2BP1, HNRNPA2B1, FTO, WTAP promote the EC progression, but METTL3, METTL14, YTHDF2 work as tumor suppressors in EC." (PMID 39582531, 2024). "In tumor samples of head and neck squamous cell carcinoma (HNSC), it was found that the fat oxidation enzyme FTO is overexpressed and positively regulates the expression of the HOXD1 gene in an m6A-dependent manner." (PMID 39192357, 2024).
tumor (continued). "For the demethylase FTO, it was found that upregulation of FTO further enhances ZEB1 expression by decreasing RNA methylation, thereby increasing chemotherapy resistance in tumour cells." (PMID 38572667, 2024). "There is growing evidence that FTO and ALKBH5 are promising new treatment targets for several human disorders, particularly tumours." (PMID 38572667, 2024). "Research has shown that FTO can directly upregulate LILRB4 via the M6A mechanism, promoting tumor invasion and suppressing T-cell activity." (PMID 38834851, 2024). "For example, FTO is involved in the degradation of miR-1266 or reducing expression levels of STAT3, cyclin D, and MMPs to stimulate tumor growth." (PMID 39136000, 2024). "Our findings show that FTO, SLC7A11, and GPX4 protein are also highly expressed in patient tumor tissues than in normal tissues, respectively." (PMID 38600610, 2024). "The exosomal Piwi-interacting RNA-17560 derived from senescent neutrophils enhances the stability and expression of ZEB1 transcript by upregulating FTO levels, leading to chemical resistance and EMT in tumor cells." (PMID 39054967, 2024). "Two potent small-molecule FTO inhibitors (CS1, CS2) were reported the following year, showcasing robust anti-tumor effects across various cancer types." (PMID 39192357, 2024). "Finally, the balance between FTO acting as a tumor promoter and suppressor may be influenced by other factors, such as mutations and the altered expression levels of key transcription factors, which are very reliant on the tissue type or even the different cancer types." (PMID 38384328, 2024). "Following FTO, ALKBH5 was identified as the second m6A demethylase, involved in the biological progression of various cancers and exhibiting both oncogenic and tumor‐suppressive functions." (PMID 39445003, 2024). "Knockdown of FTO expression in OSCC cell lines enhances autophagic flux and suppresses malignant tumor behavior." (PMID 38576024, 2024). "An FTO knockdown disturbed the glycolytic activity of tumor cells, thus restoring the function of CD8+ T cells, thereby inhibiting tumor growth." (PMID 39329974, 2024). "Given the pivotal role of FTO in CAF-mediated angiogenesis and the critical role of angiogenesis in tumor progression and spread, the authors proposed FTO as a promising antiangiogenic therapeutic target to improve CM treatment." (PMID 39518125, 2024). "We then utilized the tumor-derived CRC cell line HCT-116 and examined the impact of FTO or ZBTB48 depletion on cell proliferation." (PMID 39300486, 2024). "ALKBH5 and FTO immunostaining in the OSCC group were observed in both the peripheral and central areas of the tumor islands." (PMID 36582218, 2023). "Xu and her colleagues discovered that tumour-derived FTO dampens CD8+T cell activation and effector function by rewiring tumour glycolysis." (PMID 36859310, 2023). "The combination of m6A-targetting drugs such as FTO- and METTL3-inhibitors alongside existing anti-cancer therapy has been shown to sensitise tumours to treatment, demonstrated in animal models of a range of cancers types." (PMID 37444417, 2023). "Of these, one of the most discussed is m6A ‘erasers’ FTO, which is frequently observed to be downregulated in GBM relative to other tumours and control tissue." (PMID 36831575, 2023). "METTL3, FTO, and IGF2BP2 have been shown to function as tumour promoters through the C-myc pathway in an m6A-dependent manner in a range of cancers." (PMID 37444417, 2023). "FTO promoted OSCC tumorigenesis by enhancing the eIF4G1 stability, thereby decreasing the autophagic process and inducing tumor occurrence." (PMID 36582218, 2023). "Growing evidence has shown that FTO- and ALKBH5-mediated m6A demethylation is involved in various tumours, displaying biological context-dependent functions." (PMID 36859310, 2023). "Inhibition of FTO promotes cancer stem cell properties in CRC including sphere formation, tumor development and chemoresistance." (PMID 36874096, 2023).
tumor (continued). "FTO overexpression is correlated to a poor prognosis in HCC, and FTO knockdown decreases proliferation and in vivo tumor development while inducing G0/G1 phase arrest." (PMID 39188344, 2023). "Other studies have found that the SPI1 inhibitor DB2313 can restore endogenous FTO expression and reduce the tumor burden of GBM, indicating that FTO is a promising new prognostic indicator and therapeutic molecular target for GBM." (PMID 37964279, 2023). "In this study, we demonstrated for the first time that RNA demethylases FTO and ALKBH5 were aberrantly upregulated in uLMS and exhibited an essential tumor-promoting role in uLMS." (PMID 37175660, 2023). "In conclusion, FTO-m6A-FOXO3 is the main regulatory axis, which affects the chemotherapy resistance of tumor cells by mediating differentiation in the case of abnormal modification of m6A." (PMID 37402730, 2023). "The synergistic application of FTO inhibitor and ICI restrained tumor growth, and prolonged overall survival, suggesting that targeting m6A modification regulators is a potential strategy to elevate immune checkpoint therapy efficacy." (PMID 36810108, 2023). "We believe that METTL3 or FTO inhibitors can significantly inhibit downstream targets expression in tumors with high METTL3 or FTO expression, thereby inhibiting tumor proliferation and metastasis." (PMID 39872957, 2023). "On the contrary, FTO and YTHDF2 were proved that the more they contained in tissues, the higher the tumor stage, and the worse the prognosis." (PMID 37701836, 2023). "The groups with over-expressed FTO and ALKBH5 showed a significant decrease in tumor growth, both in terms of tumor weight and volume, compared with those of the control group." (PMID 37580808, 2023). "Conversely, METLL3 overexpression or inhibition of the m6A ‘eraser’, FTO, increased m6A methylation levels and suppressed GSC self-renewal, proliferation, and tumour progression, resulting in prolonged survival of GSC-grafted mice." (PMID 36831575, 2023). "Specific inhibitors of m6A regulators have demonstrated exciting anti-tumor effects, including inhibitors of METTL3, FTO, ALKBH5, IGF2BP1, while the therapeutic effects of METTL3 activators remain unverified." (PMID 36810281, 2023). "In ESCC, FTO removes the m6A modification of LNC00022, leading to the inhibition of LNC00022 degradation via the m6A reader YTHDF2 and promoting tumor proliferation by accelerating P21 ubiquitination and degradation." (PMID 36854773, 2023). "In general, METTL3, METTL14, IGF2BP1, FTO, and ALKBH increase the level of PD-L1 on the membrane and thereby promote tumor cell immune escape." (PMID 37485079, 2023). "Just like the role of FTO in the pathogenesis of TC, ALKBH5 also regulates ferroptosis and glycolysis, thus affecting the tumor progression." (PMID 37915103, 2023). "To determine the expression pattern of FTO in PCa, we analyzed FTO expression in the TNM plot database with 329 PCa tumor samples and 106 normal samples." (PMID 37529797, 2022). "To further clarify the regulation of FTO to EGR2 in vivo, we detected EGR2 expression in tumor tissue." (PMID 37529797, 2022). "In order to further verify the role of FTO in PTC, in vivo experiments with subcutaneous tumor models were implemented." (PMID 35721711, 2022). "To further validate the results, we obtained 60 paired tumor tissues and adjacent normal tissues of ESCC, and qRT-PCR was used to determine the expression pattern of METTL3, METTL14, WTAP, FTO, ALKBH5, YTHDF1 and YTHDF2." (PMID 35399719, 2022). "Various m6A methylation enzymes, such as METTL3, FTO, and ALKBH5, clearly affect key cellular processes in tumor cells, including apoptosis, resulting in resistance to radiation therapy." (PMID 35794625, 2022). "Blue background indicated the most significant genes down-regulated in tumor tissues, including YTHDC1, YTHDC2, METTL16, and FTO." (PMID 35581263, 2022).
tumor (continued). "So, it was shown that FTO knockdown has the opposite effect in in vitro and in vivo experiments: inhibited GSC growth and self-renewal in vitro inhibits tumor progression and increases the lifespan of GSC-grafted mice in vivo." (PMID 36012529, 2022). "In lung adenocarcinoma, the Wnt/β-catenin signaling can inhibit FTO expression, under the effect combined with YTHDF1, the increasing m6A level of c-Myc can promote tumor glycolysis and tumorigenesis." (PMID 35022030, 2022). "FTO knockout suppresses the expression of c-Jun, JunB, and c/EBPβ, thereby impairing glycolysis and restoring CD8+ T cell function, which inhibits tumour growth." (PMID 36358640, 2022). "Here, we uncover a critical role of the PIKE-A/STAT3/FTO/SDHA axis in promoting mitochondrial metabolism, which was a benefit for tumor growth." (PMID 36232604, 2022). "Compared with normal counterparts, 4 DEMGs (FTO, ZC3H13, METTL14 and RBM15B) were significantly down-regulated in tumor samples, while the remaining 11 genes were upregulated in tumor samples." (PMID 36536402, 2022). "According to our study, upregulated FTO decreased EGR2 methylation level, which promoted the expression of EGR2 and inhibited tumor growth of PCa." (PMID 37529797, 2022). "However, the possible role of FTO in ccRCC tumor progression remains unknown." (PMID 36263177, 2022). "FTO negatively regulates the expression of Ankyrin Repeat and SOCS Box Containing 2 (ASB2) and Retinoic Acid Receptor Alpha (RARA), a cluster tumor suppressor target gene, by post-transcriptionally modulating its m6A abundance and then affecting its stability." (PMID 35422475, 2022). "However, in VHL-deficient cells with high FTO expression, PGC-1α expression is induced via a decrease in m6A methylation, which restores mitochondrial activity and promotes oxidative stress (OS) and ROS production, with consequent inhibition of tumor progression." (PMID 35794625, 2022). "At present, the studies regarding ALKBH5, FTO genes were mainly focused on cancer, and ALKBH5, FTO had been identified as important malignant regulators of tumor cell phenotypes and therapeutic responses." (PMID 36619747, 2022). "With the development of high-throughput sequencing, sporadic studies have revealed that m6A regulators METTL3, FTO, and HNRNPA2B1 are aberrantly expressed in EC and affect the metastasis and invasion of a tumor by affecting the stability of mRNA." (PMID 36364436, 2022). "Between 2012 and 2019, researchers developed and identified a set of FTO inhibitors, such as rhein, MO-I-500, meclofenamic acid (MA), fluorescein, 2-hydroxylglutarate (R-2HG), FB23, and FB23-2, that showed marked anti-tumor effects in vitro and in vivo." (PMID 35296338, 2022). "Studies of the same tumor conducted by different researchers revealed that the m6A-related proteins METTL3 and FTO were important, although different results were obtained." (PMID 35155557, 2022). "Depletion of ALDOA leads to depletion of lactate and attenuation of tumor growth, whilst knockdown of YTHDF2 rescues ALDOA expression in FTO-silenced HCC cells, implying its role in posttranscriptional regulation of ALDOA under hypoxia conditions." (PMID 36289851, 2022). "FTO is able to inhibit the occurrence of PTC by downregulating SLC7A11 in m6A independently, and it functions as a tumor suppressor gene in PTC." (PMID 35721711, 2022). "To further investigate the in vivo roles of FTO/PHF1 axis in LUAD, we utilized the modified H1299 cells to perform the subcutaneous tumor model incorporating three groups (shCtrl+vector, shFTO+vector, shFTO+PHF1)." (PMID 35945194, 2022). "Initial studies showed that FTO is highly expressed in AML and exerts its oncogenic function by reducing m6A levels in the mRNA of the tumour suppressors RARA and ASB2, leading to inhibition of their expression." (PMID 33461542, 2021).